SNORD115-12 (small nucleolar RNA, C/D box 115-12)
Synonyms: HBII-52-12
Gene: Small nucleolar RNA gene on chromosome 15 (25,191,416 to 25,191,497, forward strand). Ensembl gene ENSG00000199453.
Gene Ontology:
Biological process: RNA processing
Cellular component: nucleolus
Homologues: Orthologues: chimpanzee SNORD115 (100% identical), macaque SNORD115 (100% identical). Paralogues in human: SNORD115-9 (100% identical), SNORD115-10 (99% identical), SNORD115-11 (99% identical), SNORD115-13 (99% identical), SNORD115-20 (99% identical), SNORD115-29 (99% identical), SNORD115-36 (99% identical), SNORD115-40 (99% identical), SNORD115-42 (99% identical), SNORD115-43 (99% identical), SNORD115-5 (99% identical), SNORD115-14 (98% identical), and 37 more.